Y_RNA (Y RNA )
Gene: Miscellaneous RNA gene on chromosome 15 (30,673,750 to 30,673,843, forward strand). Ensembl gene ENSG00000206846.
Homologues: Orthologues: guinea pig Y_RNA (88% identical). Paralogues in human: Y_RNA (94% identical), Y_RNA (89% identical), Y_RNA (88% identical), RNY3 (87% identical), Y_RNA (87% identical), RNY3P14 (86% identical), Y_RNA (86% identical), RNY3P1 (85% identical), Y_RNA (85% identical), Y_RNA (84% identical), RNY3P16 (83% identical), Y_RNA (83% identical), and 94 more.